FABP7 (fatty acid binding protein 7)
Diseases named in the same sentence as FABP7 in open-access papers (continued):
Sharing a sentence is not in itself a finding about the gene and the disease.
tumor (continued). "Maintenance of a signature gene expression pattern was largely uniform across the heterogeneous set of tumors analyzed, with the exception of FABP7, a gene for which expression was not maintained from any tumor or under any culture condition tested." (PMID 26317980, 2015). "This dramatic effect on tumor cell growth did not allow to obtain enough cells to perform in vitro and in vivo experiments testing the effects of FABP7 inhibition." (PMID 23284888, 2012). "We previously analyzed FABP7 mRNA expression in primary surgically resected RCCs and were able to detect FABP7 mRNA in the tumor, but not in normal tissue." (PMID 21771320, 2011). "No clear differences were observed between FABP7 expression levels in cell lines originating from primary tumor vs. metastasis." (PMID 18826602, 2008). "Similarly, FABP7 can be upregulated by HIF-1α to enhance DGAT1 activity in macrophages, which in turn delivers lipids to CD8+ T-cells and tumor cells via exosomes, resulting in CD8+ T-cell dysfunction and tumor cell proliferation." (PMID 41226585, 2025). "However, the functions and molecular mechanisms of FABP7 in the tumor microenvironment (TME) have not yet been reported." (PMID 40765822, 2025). "Finally, FABP7 KO did not reduce the number or impair the function of regulatory T cells (Tregs) in MC38 tumor-bearing mice." (PMID 40765822, 2025). "Two of the 10 patients with OAC have died; one tumor had no detectable Id4 and FABP7 immunoreactivity, while the other one showed a similar degree of cytoplasmic/nuclear FABP7 and cytoplasmic Id4 staining to the other 4 specimens derived from patients who were still alive." (PMID 16018821, 2005). "There are also a number of samples that appear to have relatively high tumor content (>1%) for SCGB2A2 and FABP7, but for which the genes are not detected in cfRNA, suggesting that other factors beyond tumor tissue expression may influence the detectability of a given biomarker in circulation." (PMID 33883548, 2021). "Real time PCR and Western blot analysis revealed that FABP7 was uniquely expressed in neurospheres and almost absent in adherent cells independent of whether the cells were derived from a primary or a recurrent tumor." (PMID 23284888, 2012). "Interestingly, such a change of FABP7 expression cannot be found by bulk-based methods, e.g., in the TCGA dataset between metastatic versus non-metastatic NSCLC tumor masses (data not shown)." (PMID 35269427, 2022). "However, mRNA expression levels of FABP1, FABP2, FABP5, FABP6, FABP7, FABP9, or FABP12 did not significantly differ in different tumor stages in CRC patients." (PMID 34680577, 2021). "Moreover, the intra-cranially growing tumor derived from shFABP7 transduced cells showed a significantly lower DCX expression than in scrambled NS (***p<0.001), suggesting that FABP7 play a role in the invasion rather than in the proliferative process." (PMID 23284888, 2012). "DEGs between FABP7 positive and negative tumor cells displayed significantly overrepresented GO categories related to changes in metastatic competency (cell adhesion/migration/spreading), and GSEA suggested positive correlations between FABP7 and tumor metastasis." (PMID 35269427, 2022).
cancer (39 papers, 2011 to 2025). A tumor composed of atypical neoplastic, often pleomorphic cells that invade other tissues. "A heatmap analysis of the differentially expressed genes showed that most of the genes associated with signaling pathways in cancer were more highly expressed in FABP7 OV astrocytes than in CTL astrocytes." (PMID 39596296, 2024). "In addition, FABP7 overexpression in astrocytes led to the upregulation of most cancer-associated genes, suggesting a potential role for FABP7 in shaping the oncogenic gene expression landscape." (PMID 39596296, 2024). "Research on cancer has similarly documented FABP7’s cytoplasmic and metabolic functions, such as modulating fatty acid uptake and processing, lipid droplet formation, and oncogenic signaling pathways." (PMID 39596296, 2024). "Here, we propose a FABP7-mediated cellular signaling model applicable to neurodegenerative disease that is supported by evidence derived from FABP7 studies in other diseases, particularly cancer." (PMID 35844236, 2022). "It is notable that FABP7 and AR were selected as differentially expressed genes which were upregulated in cancer cells in metastatic lymph nodes." (PMID 33816302, 2021). "The cancer cells with FABP7 knockdown expressed high level of UCP1 and increased cellular temperature." (PMID 32647572, 2020). "FABP7 preferentially binds to polyunsaturated fatty acids (PUFAs), and its knockdown led to increased ROS in cancer cells under hypoxia and hypoxia-reoxygenation, potentially due to loss of its PUFA-scavenging function." (PMID 32647572, 2020). "Our immunohistochemical analysis showed that higher FABP7 expression significantly correlated with distant metastasis and poor cancer-specific survival (CSS; both p < 0.05)." (PMID 30442117, 2018). "Further, inhibition of FABP7 expression by siRNAs significantly decreases the ability of certain human cancer cell lines to migrate." (PMID 28292269, 2017). "In apparent contradiction to this, inhibition of FABP7 expression by small interfering RNAs (siRNAs) significantly reduces the proliferation of certain human cancer cell lines, and overexpression of FABP7 stimulates the proliferation of RCC cell lines." (PMID 28292269, 2017). "From this limited gene list, carboxypeptidase E (CPE), fatty acid binding protein 7 (FABP7) and peroxisomal membrane protein 2 (PXMP2) were all previously found to be associated with human cancer." (PMID 29062039, 2017). "Our finding of strong FABP7 mRNA expression by two of six RCC cell lines varies from our previous finding of 80% (n = 54) overexpression by carcinoma compared to corresponding expression in normal tissues." (PMID 21771320, 2011). "In this analysis, FABP7 expression displayed a significantly higher correlation with increased cancer risk in LGG but not GBM, compared to other cancer types." (PMID 39596296, 2024). "Building on the signaling cascades and mechanisms seen in cancer, we propose a novel role for FABP7 in sleep and AD pathogenesis in which ligand availability determines FABP7’s function, with DHA promoting neuroprotection and normal sleep, and AA promoting disrupted sleep and AD pathogenesis." (PMID 35844236, 2022). "Our results suggest that increasing DHA content in the GBM microenvironment may reduce the migration/infiltration of FABP7-expressing neural stem-like cancer cells." (PMID 34444824, 2021). "The effect of the FABP7 knockdown on the viability of cancer cells was tested." (PMID 32647572, 2020). "This suggested that FABP7 might be more effective in protecting cancer cells from ROS damage than UCP1." (PMID 32647572, 2020). "Taken together, FABP7 could be a potential target for cancer therapy that affects the sensitivity to oxidative stress and γ-irradiation although its prognostic impact remains to be further investigated." (PMID 32647572, 2020).
cancer (continued). "In contrast, heterogeneous distribution of mRNA expression of FABP7 with a higher average value leads to the hypothesis that FABP7 may be involved in cancer progression in ccRCC." (PMID 30442117, 2018). "Pathway and gene enrichment analysis of RNA sequencing data from wild-type (WT) and Fabp7-knockout (KO) mouse brains, alongside control (CTL) and FABP7-overexpressing (FABP7 OV) human astrocytes, revealed a more pronounced effect of FABP7 levels on multiple cancer-associated pathways." (PMID 39596296, 2024). "Notably, uptake of both MUFAs and PUFAs was equal between FABP7-knockdown and control cancer cells." (PMID 31819188, 2020). "Thus, an effect of FABP7 on differentiation in the cancer cells is plausible." (PMID 32647572, 2020). "In GBM, FABP7 increases the accumulation of monounsaturated fatty acids (MUFA) and triglycerides, inhibiting lipid peroxidation and helping cancer cells resist ferroptosis." (PMID 40717587, 2025). "FABP7 is a member of the FABP family, which is known to have family members 1 to 7 in cancer tissue." (PMID 30442117, 2018). "Particularly, FABP7, involved in fatty acids uptake, is induced by HIF-1α, leading to the accumulation of LDs and contributing to cancer cell growth." (PMID 29312541, 2017). "Another characteristic phenotype of cancer cells is the alteration of cell receptors, such as high glutamine uptake by an elevated expression of glutamine transporters and the overexpression of fatty acid-binding receptor proteins like ADRP, FABP3, and FABP7." (PMID 39772236, 2024). "The precise mechanisms of FABP7’s effects on chemosensitivity and prognosis are unclear, but they may involve increased DHA uptake facilitated by FABP7 in malignant tumor cells, as was reported for GBM NSCs." (PMID 39596296, 2024). "Cancer progression has been proposed to be mediated not directly through FABP7 expression, but rather via the subcellular trafficking of fatty acids by FABP7." (PMID 35844236, 2022). "Although more studies are needed to elucidate the molecular mechanisms linking FABP7-related fatty acid metabolism and UCP1 induction, our findings illustrate a new metabolic adaption of cancer cells that involves heat production similar to that used by beige adipocytes." (PMID 32647572, 2020). "Several other candidate genes were found to be undetectable in whole blood, while most of the genes that were detectable (EGLN3, CAV2, ESM1, TMEM45A, NOL3, FABP7) did not exhibit significant dysregulation in expression between cancer and healthy PAXgene samples." (PMID 32013938, 2020). "Notably, MYB, KIT, and FABP7 (the top-ranked signature genes) directly interact with NOTCH1, and these interactions have been reported to be involved in regulating cancer stem cell differentiation." (PMID 36879115, 2023). "In our cohort, other known prognostic factors (pT stage, grade, Hb, neutrophil, LDH, CRP, Na, corrected calcium) could not show significant correlation with cancer-specific survival (CSS), while FABP7 could be a prognostic marker." (PMID 30442117, 2018).
neurological disorders (7 papers, 2014 to 2025). "Many diseases, nervous system dysfunction, and neurological disorders are associated with alterations in FABP7 expression." (PMID 37404868, 2023).
psychiatric diseases (5 papers, 2014 to 2026). "Fatty acid-binding protein 7 (FABP7) assists in the intracellular trafficking of endogenous cannabinoids and polyunsaturated fatty acids (PUFAs) and has been implicated for various psychiatric diseases." (PMID 42009986, 2026). "Fabp7 gene encodes the brain fatty acid binding protein that regulates hippocampal functions such as neurogenesis and behavior and may be associated with psychiatric disorders." (PMID 26556046, 2015).
neurodegenerative disease (4 papers, 2021 to 2025). A disorder of the central nervous system characterized by gradual and progressive loss of neural tissue and neurologic function. "Reflecting its critical role in neural physiology and function, growing evidence suggests that FABP7 is implicated in the pathophysiology of neurological and neurodegenerative diseases, particularly AD." (PMID 41154661, 2025). "Brain-type fatty acid binding protein (FABP7) is enriched in astrocytes and has been implicated in sleep/wake regulation and neurodegenerative diseases; however, the precise mechanisms underlying the role of FABP7 in these biological processes remain unclear." (PMID 35844236, 2022). "Since sleep and circadian disruptions influence neurodegenerative diseases, we sought to determine whether FABP7 plays a role in AD pathophysiology and found that Aβ-induced sleep fragmentation in an Aβ fly model was rescued by overexpression of mouse FABP7 or the fly homolog, dFABP." (PMID 41154661, 2025). "The association between FABP7 and PPI status suggests roles of the FABP7 gene in the pathology of PPI-mediated neuropsychiatric and/or neurodegenerative diseases." (PMID 34208549, 2021).
dermatosis (1 paper, 2022). "We also performed the division of psoriatics according to the duration of the dermatosis–less or more than 20 years–and looked for changes in FABP-7 concentrations before and after the treatment and correlations with laboratory parameters." (PMID 35566558, 2022).
gastrointestinal tumors (1 paper, 2025). "Notably, FABP7 expression was minimal to undetectable in macrophages from the lung, bone, or spleen—common metastatic sites for gastrointestinal tumors—during the PMN phase." (PMID 40765822, 2025).
infection (1 paper, 2025). The state of being infected such as from the introduction of a foreign agent such as serum, vaccine, antigenic substance or organism. "The downregulated lncRNA A230001M10Rik is strongly correlated with Fabp7, Slc2a5, and Depdc7, which might suggest potential roles in neural homeostasis, glial metabolism, and cellular proliferation during infection." (PMID 41214723, 2025).
nervous system tumors (1 paper, 2022). "Fatty acid binding protein 7(FABP7), which regulates intracellular lipid metabolism, is highly expressed in nervous system tumors, but its prognostic value remains undetermined." (PMID 35783014, 2022).
FABP7 also shares sentences with these, for which no sentence is quoted: Parkinson disease (4 papers); medulloblastoma (3); Stroke (3); Hepatic steatosis (2); oligodendroglioma (2); acute myocardial infarction (1); astrocytic tumor (1); atherosclerosis (1); atopic dermatitis (1); attention deficit-hyperactivity disorder (1); brain diseases (1); cardiovascular disorder (1); cervical cancer (1); Cognitive impairment (1); Coma (1); cortical dysplasia (1); cyst (1); diffuse astrocytoma (1); embryonic carcinoma (1); gastric carcinoma (1); head and neck cancer (1); heart failure (1); Hodgkins lymphoma (1); Insulin resistance (1); leishmaniasis (1); lipid metabolism disorder (1); lung carcinoma (1); mental disorder (1); metabolic dysfunction-associated steatohepatitis (1); Obesity (1).
A further 16 diseases each share a sentence with FABP7 in 1 paper.